EPHA4 (EPH receptor A4)
Diseases named in the same sentence as EPHA4 in open-access papers (continued):
Sharing a sentence is not in itself a finding about the gene and the disease.
amyotrophic lateral sclerosis (23 papers, 2013 to 2024). Amyotrophic lateral sclerosis (ALS) is a neurodegenerative disease characterized by progressive muscular paralysis reflecting degeneration of motor neurons in the primary motor cortex, corticospinal tracts, brainstem and spinal cord. "For example, elevated EphA4 signaling results in neuronal damage in Alzheimer’s disease and amyotrophic lateral sclerosis (ALS), and the loss of EphB2/B3 signaling is implicated in skeletal malformations that cause cleft palate." (PMID 33277361, 2021). "Several members of the ephrin-A system including EphA1, EphA4, ephrin-A1, and ephrin-A5 have been associated with a diversity of neurodegenerative conditions such as Alzheimer’s disease or amyotrophic lateral sclerosis." (PMID 32629797, 2020). "Reduced EphA4 expression is associated with enhanced survival of amyotrophic lateral sclerosis patients and in animal models of this pathology." (PMID 32629797, 2020). "Ephrin type-A receptor 4 (EphA4) has been implicated in the disease pathology of Alzheimer’s, amyotrophic lateral sclerosis, ischemia, and in TBI." (PMID 31711546, 2019). "In recent years, EphA4 agonists have been proposed for a variety of therapeutic applications, including amyotrophic lateral sclerosis and prostate cancer." (PMID 38258903, 2024). "Except for ischemia, EphA4 also plays important role in the pathogenesis of neurological disorders such as Alzheimer's disease (AD), amyotrophic lateral sclerosis (ALS) and glaucoma." (PMID 37519758, 2023). "Furthermore, EphA4 has been implicated in neurodegenerative diseases such as amyotrophic lateral sclerosis (ALS) and Alzheimer’s disease." (PMID 34139238, 2021). "Other research reported that genetic as well as pharmacological inhibition of EphA4 signaling increases survival in a disease modifier of amyotrophic lateral sclerosis (ALS)." (PMID 31798398, 2019). "This would parallel the situation in amyotrophic lateral sclerosis where motor neurons having high levels of the growth repellant factor EPHA4 are the neurons that are unable to sprout and reconnect with muscle targets and which are consequently lost first in disease." (PMID 34305528, 2021). "Previously, we identified EphA4 as a genetic modifier of amyotrophic lateral sclerosis (ALS) in both zebrafish and rodent models, via modulation of the intrinsic vulnerability, and re-sprouting capacity of motor neurons." (PMID 31803009, 2019). "Previously we identified EphA4 as a modifier of amyotrophic lateral sclerosis (ALS) in both zebrafish and rodent models." (PMID 31803009, 2019). "In addition, EphA4 has been found to play a role in cancer biology as well as in the pathogenesis of several neurological disorders such as stroke, spinal cord injury, multiple sclerosis, amyotrophic lateral sclerosis (ALS), and Alzheimer's disease." (PMID 28526745, 2017). "In humans with amyotrophic lateral sclerosis (ALS), EphA4 expression inversely correlates with disease onset and survival." (PMID 24265799, 2013). "EPHA4 has been proposed as a disease modifier gene of amyotrophic lateral sclerosis (ALS)." (PMID 36942388, 2023). "In a previous study, EphA4 expression was correlated with the prognosis of patients with amyotrophic lateral sclerosis (ALS), and blocking EphA4 with compound 1 increased the survival of ALS models in vivo." (PMID 26516928, 2015).
Alzheimer disease (16 papers, 2011 to 2025). A progressive, neurodegenerative disease characterized by loss of function and death of nerve cells in several areas of the brain leading to loss of cognitive function such as memory and language. "Loss of EphA4 improved social memory in a mouse model of Alzheimer’s disease in association with alterations in spine morphology." (PMID 31831046, 2019). "Increased EPHA4 signaling but decreased EPHB2 signaling have been reported to exacerbate Alzheimer’s disease pathology in mouse models." (PMID 39706267, 2024). "Current studies have shown that EphA4 inhibitors have neuroprotective effects on Alzheimer's disease, spinal cord injury, and stroke in mouse models." (PMID 37064501, 2023). "For instance, EphA4 is a substrate of γ-secretase, a protease dysfunctioning in many early-onset Alzheimer’s disease cases, and this member of the EphA family controls the metabolism of the amyloid precursor protein." (PMID 32629797, 2020). "The receptor tyrosine kinase, erythropoietin-producing hepatocellular A4 (EphA4), was recently identified as a molecular target for Alzheimer’s disease (AD)." (PMID 29743517, 2018). "Our results support the notion that EphA4/c-Abl signalling contributes to the development of early cognitive impairments in Alzheimer's disease patients." (PMID 24658113, 2014). "Although EphA4 expression levels decrease in adult life, EphA4 is considered as a major contributor in neurological disorders such as spinal cord injury, stroke, and Alzheimer’s disease." (PMID 31803009, 2019). "EphA4-c-Abl activation may be a key pathway that is altered in the early stages of Alzheimer's disease, when synaptic damage begins to occur." (PMID 24658113, 2014). "EphA4/c-Abl signalling pathway could be a relevant in the early cognitive decline observed in Alzheimer's disease." (PMID 24658113, 2014). "EphA4/c-Abl signalling could be a relevant pathway involved in the early cognitive decline observed in Alzheimer's disease patients." (PMID 24658113, 2014). "One EphA4 inhibitor, the KYL peptide, has been studied extensively in models of neurological disorders, such as acute injuries including spinal cord injury and stroke and neurodegenerative disorders such as ALS and Alzheimer's disease." (PMID 28526745, 2017).
melanoma (13 papers, 2016 to 2025). A malignant, usually aggressive tumor composed of atypical, neoplastic melanocytes. "This EPHA4 mutation is a confirmed somatic PV that has been described in five cutaneous malignant melanoma patients, and in a patient with a serous endometrial carcinoma." (PMID 41516312, 2025). "Mutation of Leucine 920 to Phenylalanine (L920F) in EphA4 Sam domain has been related to melanoma through enhanced EphA4 autophosphorylation." (PMID 36142306, 2022). "We show here that the L920F gain-of-function mutation identified in a melanoma metastasis (cbioportal.org) involves a leucine in the EphA4 SAM domain that is conserved in all Eph receptors." (PMID 34139238, 2021). "A search for EphA4 gain-of-function mutations in melanoma uncovered a mutation of the highly conserved leucine 920 in the EphA4 sterile alpha motif (SAM) domain." (PMID 34139238, 2021). "Here we show that the EphA4 L920F melanoma mutation, which is located in the SAM domain, induces dysregulated receptor autophosphorylation and signaling." (PMID 34139238, 2021). "In agreement with a dual role of EphA4 even in the same tumor type, our analysis of EphA4 melanoma mutations identified two mutations (G733W and R745C) that abrogate EphA4 kinase activity and the L920F mutation, which increases kinase activity." (PMID 34139238, 2021). "EphA4 activating mutations, such as L920F, could promote malignancy in melanomas in which ligand-dependent EphA4 activation is low." (PMID 34139238, 2021). "This suggests that high EphA4 activation may promote melanoma malignancy and, therefore, that EphA4 activating mutations may play a role in melanoma progression." (PMID 34139238, 2021). "EPHA4 downregulation increases pERK, proliferation, migration, and metastasis in melanoma, and is inversely correlated with overall survival." (PMID 36765910, 2023). "In melanoma large EphA4 mRNA expression has been related to poor patient survival and increased EphA4 signaling is thought to contribute to melanoma evolution." (PMID 36142306, 2022). "Quantitative real-time polymerase chain reaction (qRT-PCR) was used to detect the expression of miR-106b-5p and EphA4 in melanoma tissues." (PMID 33741023, 2021). "We focused on the L920F gain-of-function mutation because patient survival analyses suggest a correlation between EphA4 activation and melanoma malignancy." (PMID 34139238, 2021). "Melanoma cell-derived exosomal miR-106b-5p promotes melanocyte EMT by directly repressing EphA4 to activate ERK pathways, leading to the establishment of a tumour metastasis-supporting microenvironment." (PMID 33741023, 2021). "Deletion of EPHA4 and EPHA7 loci in thick melanomas is consistent with decreased expression of EPHA4 and EPHA7 mRNA in metastatic compared to primary melanomas." (PMID 27095580, 2016). "This suggests the potential clinical relevance of EphA4 mutations as part of a constellation of gene mutations cooperating to promote melanoma progression in tumors lacking a dominant driver mutation." (PMID 34139238, 2021). "A correlation between decreased patient survival and high EphA4 mRNA expression in melanoma tumors that also highly express ephrinA ligands suggests that enhanced EphA4 signaling may contribute to melanoma progression." (PMID 34139238, 2021). "In addition, EphA4 has been proposed to play a role in different cancers, including melanoma, breast cancer, glioma, hematologic malignancies, pancreatic cancer, prostate cancer, and lung cancer as well as in resistance to chemotherapy and radiotherapy." (PMID 34139238, 2021). "Interestingly, in melanoma, a cancer derived from cells of neural crest origin, EphA4 is preferentially mutated in tumors lacking major driver mutations." (PMID 34139238, 2021). "miR-519d could promote melanoma progression by downregulating EphA4, among other mechanisms." (PMID 29743816, 2018).
melanoma (continued). "Among these candidates, EphA4 was shown to function as a negative regulator of the EMT and metastasis of melanoma cells and was chosen for further study." (PMID 33741023, 2021). "EphA4 effectively suppresses the EMT and metastatic capabilities of melanoma cells by interfering with the activation of ERK." (PMID 33741023, 2021). "Moreover, EPHA4 has been reported to inhibit the EMT and metastasis of melanoma cells by interfering with ERK activation." (PMID 33741023, 2021). "EphA4 could interfere with the activation of ERK, which is a major pathway that mediates melanoma cell migration and invasion." (PMID 33741023, 2021). "Spearman’s correlation between the miR-106b-5p and EphA4 mRNA levels was negative in 36 melanoma tissues." (PMID 33741023, 2021). "Furthermore, melanoma cells (A375, A2058, SK-MEL-28 and SK-MEL-28) expressed lower EphA4 levels compared to human epidermal melanocytes (HEMa-LP)." (PMID 33741023, 2021). "Deletion of EPHA4 and EPHA7 loci, that we found in two out of five thick melanomas, correlates with their reduced expression in metastatic compared to primary melanomas, suggesting that EPHA4 and EPHA7 might act as tumor suppressor during melanoma progression." (PMID 27095580, 2016). "According to the original MPAS report, EPHA4 contributes significantly to MPAS in lung cancer and melanoma, but is virtually without effect in colorectal cancer, confirming its tissue-specific nature." (PMID 36362153, 2022).
pancreatic cancer (10 papers, 2011 to 2025). "The results demonstrated cytostatic efficacy in PDAC cells expressing EphA4, both in vitro and in orthotopic pancreatic cancer models, by suppressing the phosphorylation of EphA4 and Akt, and inducing apoptosis." (PMID 39839790, 2024). "In this context, EphA4 promotes the motility and invasion of pancreatic cancer cells in part through the downregulation of E-cadherin." (PMID 30639848, 2019). "The results demonstrated that the knockdown of EPHA4 by siRNA inhibits the motility and invasion of pancreatic cancer cells." (PMID 24932309, 2014). "The expression of EPHA4 in pancreatic cancer cell lines (MIA PaCa-2, HAPC, SW1990, BxPC-3 and Panc-1) was examined by western blotting." (PMID 24932309, 2014). "Next, an invasion assay was performed to determine the function of EPHA4 in pancreatic cancer cell invasion." (PMID 24932309, 2014). "Wound healing and invasion assays were then performed to assess the effect of EPHA4 knockdown on the motility and invasion of pancreatic cancer cells." (PMID 24932309, 2014). "High expression of EPHA4 but reduced expression of EPHB2 is linked with liver metastasis in human colon carcinomas, while high EPHA7 protein expression is associated with worse prognosis in patients with pancreatic cancer." (PMID 35204461, 2022). "Furthermore, overexpression of EPHA4 promotes the growth of pancreatic cancer cells and enhances the proliferation and migration of glioma cells." (PMID 24932309, 2014). "The present study revealed that EPHA4 was greatly expressed in the pancreatic cancer cells." (PMID 24932309, 2014). "EPHA4 was significantly expressed in all the examined pancreatic cancer cells." (PMID 24932309, 2014). "Upregulation of EPHA4 has been found in various types of tumors, such as gastric, colorectal and pancreatic cancer, and high expression of EPHA4 has been found to correlate with tumor progression, including the invasion, pathological stage and distant metastasis." (PMID 24932309, 2014). "Next, a wound healing assay was performed in Panc-1 and BxPC-3 cells and the results showed that the motility of EPHA4 siRNA-transfected cells was significantly reduced compared with the control siRNA cells, which indicated that EPHA4 enhances the motility of pancreatic cancer cells." (PMID 24932309, 2014). "In conclusion, the current study demonstrated that EPHA4 may promote the motility and invasion of pancreatic cancer cells." (PMID 24932309, 2014). "In addition, the knockdown of EPHA4 by siRNA inhibited the motility and invasion of pancreatic cancer cells, which indicated the involvement of EPHA4 in the motility and invasion of pancreatic cancer cells." (PMID 24932309, 2014). "Thus, the results indicated that EPHA4 affects the expression of E-cadherin and Snail in pancreatic cancer cells." (PMID 24932309, 2014). "Overall, these results suggested that EPHA4 may promote the motility and invasion of pancreatic cancer cells via the upregulation of MMP-2 and Snail, as well as the downregulation of E-cadherin." (PMID 24932309, 2014). "Notably, the knockdown of EPHA4 was found to suppress the invasion of Panc-1 and BxPC-3 cells, which suggested that EPHA4 is involved in the invasion of pancreatic cancer cells." (PMID 24932309, 2014). "Therefore, the aim of the present study was to determine the effect of EPHA4 on the motility and invasion of pancreatic cancer cells." (PMID 24932309, 2014). "EphA4-ephrinA3 pathway has been considered a promising target in pancreatic cancer cells." (PMID 23738943, 2013). "However, the role of EPHA4 in pancreatic cancer cells remains unclear." (PMID 24932309, 2014). "However, the role of EPHA4 in pancreatic cancer remains unclear." (PMID 24932309, 2014). "Thus, EPHA4 may act as a useful target for the treatment of pancreatic cancer." (PMID 24932309, 2014). "The current study demonstrated that EPHA4, a member of the EPH receptors, may promote the motility and invasion of pancreatic cancer cells." (PMID 24932309, 2014).
pancreatic cancer (continued). "The results of the current study also showed that the knockdown of EPHA4 may increase the expression of E-cadherin and decrease the expression of Snail in Panc-1 and BxPC-3 cells, which indicated that EPHA4 may be involved in the EMT process of pancreatic cancer cells." (PMID 24932309, 2014).
colorectal cancer (9 papers, 2011 to 2022). A primary or metastatic malignant neoplasm that affects the colon or rectum. "EphA4 expression has also been associated with increased chemoresistance and radiotherapy failure in colorectal cancer patients." (PMID 34943502, 2021). "Irradiation increases the activation of EphA4 in survivor colorectal cancer cells and promotes the internalization of an EphA4/E-cadherin complex, inducing cell-cell adhesion disruption." (PMID 30639848, 2019). "We examined the expression of EphrinB2 ligand and the EphrinB2 signaling receptors (EphB1, EphB2, EphB3, EphB4, and EphA4) in colorectal carcinoma." (PMID 31545551, 2019). "To evaluate the effects of EphB2 depletion, we selected the SW620 colorectal carcinoma cell line, which contains abundant EphB2, whereas EphB1, EphB3, and EphB4 are undetectable and EphA4 is detected at low levels." (PMID 31545551, 2019). "Overexpression of EphA4 gene and reduced EphB2 gene expression correlate with liver metastasis in colorectal cancer." (PMID 27487126, 2017). "This intriguing dual role of the EPHs and ephrins in both promoting and suppressing cancer has been highlighted by various expression profiling tumor studies: for instance, EPHA4 overexpression promotes gliomas, breast and colorectal cancers whereas it suppresses lung cancer." (PMID 35204461, 2022). "Similarly, EPHA4 expression has been correlated with increased chemoresistance and radiotherapy failure in colorectal cancer patients." (PMID 35626181, 2022). "In addition, EphA4 signaling regulates the aggressive phenotype of irradiated colorectal cancer cells." (PMID 30639848, 2019). "The HT‐29 colorectal carcinoma cell line, which needs EphrinB2 to survive, contains abundant EphB4 but not EphB1, EphB2, EphB3, or EphA4 proteins, as observed previously." (PMID 31545551, 2019).